MDM2 (MDM2 proto-oncogene)
Diseases named in the same sentence as MDM2 in open-access papers (continued):
Sharing a sentence is not in itself a finding about the gene and the disease.
endometriosis (5 papers, 2020 to 2025). The growth of functional endometrial tissue in anatomic sites outside the uterine body. "Besides, increased expression of MDM2 has been corroborated in endometriosis and is reportedly is closely linked to the dysfunction of normal endometrium, cell cycle, as well as the progression of endometriosis." (PMID 33987175, 2020). "The target gene for miR-92a-3p is the proto-oncogene gene mouse double minute homologue 2 (MDM2) with its role in contributing to blastocyst adhesion to the endometrium but also supporting endometriosis." (PMID 40295388, 2025). "Using a human endometrial organoid chip model, a consistent downregulation of ERα alongside upregulation of ERβ, BAG2, and MDM2 in both human endometriosis specimens and mouse models was observed in the study." (PMID 41156372, 2025). "On the other hand, overexpression of MDM2 enhanced the degradation of ubiquitination of ERα and diminished the protein expression of ERα, thus contributing to the development of endometriosis." (PMID 33987175, 2020). "The expression of ERα was downregulated while that of ERβ, BAG2, and MDM2 was upregulated in human endometriosis and in the mouse model." (PMID 33987175, 2020). "In this study we investigated the roles of two Ubiquitin E3 Ligases, namely hsc70-interacting protein (CHIP) and mouse double minute 2 (MDM2), in the abnormal estrogenic activity in endometriosis." (PMID 33987175, 2020). "The degradation of ERα by MDM2 in cultured endometriosis-HESCs also occurred through the ubiquitin-proteasome pathway." (PMID 33987175, 2020). "To evaluate the effects of BAG2 and MDM2 in vivo, we established a mouse model of endometriosis and detected." (PMID 33987175, 2020). "Although the expression of MDM2 is altered in endometriosis, the regulation of disease progression by MDM2 through ER regulation is still not well characterized." (PMID 33987175, 2020). "Besides, we found that BAG2 and MDM2 were both elevated in the endometriosis tissues compared with normal endometrium." (PMID 33987175, 2020). "Moreover, the positive expression rate of MDM2 protein was much higher in ovarian endometriosis than that in normal endometrium, thus participating in the pathogenesis and development of endometriosis." (PMID 33987175, 2020). "Our findings suggest that the interference of BAG2 and MDM2 may have therapeutic effects in endometriosis." (PMID 33987175, 2020). "Therefore, the mRNA and protein expression of MDM2 was determined in the human and mouse endometriosis/normal tissues and in the HESCs." (PMID 33987175, 2020). "Knockdown of both BAG2 and MDM2 alleviated the development of endometriosis in mice." (PMID 33987175, 2020). "Furthermore, it also validated that CHIP and MDM2 mediate the degradation of ERβ and ERα, respectively, via the ubiquitin–proteasome pathway, and that targeted interference with BAG2 and MDM2 may elicit therapeutic effects in endometriosis." (PMID 41156372, 2025).
fibrous dysplasia (5 papers, 2020 to 2024). A genetic, non-inheritable disorder caused by osteoblastic differentiation defects that result in the replacement of bone marrow and trabecular bone by fibrous stroma and immature bone. "However, other benign fibro-osseous lesions in their study also showed MDM2 gene locus amplification, including 12% of fibrous dysplasias." (PMID 39105970, 2024). "With regard to histopathologically differentiating OSJ from fibrous dysplasia and other benign fibrous and fibro-osseous lesions, immunohistochemical expression of murine double-minute type 2 MDM2) and cyclin-dependent kinase 4 (CDK4) may be helpful." (PMID 33125360, 2020).
gastric adenocarcinoma (5 papers, 2017 to 2023). "Based on these findings, we predict that EBNA1 may be linked to MDM2 and MDM4 expression levels, as well as the risk of developing gastric adenocarcinoma." (PMID 36624687, 2023). "Of these, 8 regions contained previously characterized amplified oncogenes: GATA4, CCND1, CDK6, MDM2, EGFR, MCL1, ERBB3 and MYB; this is the first report of significant and nearly isolated MYB amplification in gastric adenocarcinoma." (PMID 28426752, 2017).
heart failure (5 papers, 2017 to 2025). Inability of the heart to pump blood at an adequate rate to meet tissue metabolic requirements. "Therefore, we decided to test the physiological relevancy of main regulators in these gene sets for their ability to drive the development of heart failure associated with Mdm2 loss at an earlier time point at 7 days post-Tam." (PMID 29267372, 2017). "In our study, increased MDM2 protein expression after MI and decreased ITCH expression after CHF could promote NF-kB activity, which in turn is known to induce heart failure by triggering chronic inflammation." (PMID 34947961, 2021). "Thus, we examined the kinetics of caspase-8 (extrinsic cell death pathway) and caspase-3 (intrinsic apoptosis) activation to determine their relationship to the development of heart failure in the absence of Mdm2." (PMID 29267372, 2017).
HIV-1 infection (5 papers, 2012 to 2025). The type species of lentivirus and the etiologic agent of acquired immunodeficiency syndrome (AIDS). "Vif is ubiquitinated by the E3-ligase MDM2, and is noteworthy amongst the HIV-1 accessory proteins as it has a notably short half-life, which may suggest Vif’s intense rates of MDM2-mediated degradation are by design and benefit HIV-1 infection." (PMID 39205255, 2024).
Insulin resistance (5 papers, 2021 to 2025). Increased resistance towards insulin, that is, diminished effectiveness of insulin in reducing blood glucose levels. "Adipocyte-specific MDM2 overexpression resulted in exacerbated weight gain, insulin resistance, and decreased energy expenditure." (PMID 35747386, 2022). "Here, our study suggested that Mdm2-AKI mice displayed increased body weight, decreased energy expenditure, and exacerbated insulin resistance both on a NCD and a HFD." (PMID 35747386, 2022). "Over-stabilized MDM2 induces cytoplasmic accumulation of NDUFS1, disrupting mitochondrial super-complex assembly, enhancing ROS production, and initiating BIM-mediated BAK/BAX-dependent apoptosis—events that lead to insulin resistance." (PMID 41459066, 2025). "Additionally, our results also demonstrated MDM2 overexpression induced BAT adipocyte hypertrophy, which contributed partly to a metabolic disorder such as decreased heat production and increased insulin resistance." (PMID 35747386, 2022). "In our study, we constructed Mdm2 adipocyte-specific knock-in (Mdm2-AKI) mice and found that Mdm2-AKI mice displayed increased body weight, decreased energy expenditure, and exacerbated insulin resistance both on a normal chow diet (NCD) and a HFD." (PMID 35747386, 2022).
lung squamous cell carcinoma (5 papers, 2016 to 2025). "The results showed that the SNPs in XPC (rs2228000 and rs2228001), TP73 (rs2273953), MDM2 (rs2279744), PTEN (rs2299939) and DNA-PKcs (rs8178085 and rs12334811) genes significantly affected the sensitivity of lung squamous cell carcinoma to chemotherapy." (PMID 27246533, 2016).
malignant pleural mesothelioma (5 papers, 2015 to 2018). A malignant neoplasm that arises from mesothelial cells in the pleura and shows a diffuse growth pattern. "Previously, our group demonstrated that nuclear expression of E3 ubiquitin ligase (MDM2) in malignant pleural mesothelioma (MPM) is significantly associated with decreased overall survival." (PMID 30112000, 2018). "A recent study detected MDM2 nuclear expression in 21.3% of malignant pleural mesothelioma patients, which was correlated with worse prognosis." (PMID 28255749, 2017).
myeloid neoplasm (5 papers, 2019 to 2026). Proliferation of myeloid cells originating from a primitive stem cell.
myeloproliferative neoplasm (5 papers, 2018 to 2026). A clonal hematopoietic stem cell disorder, characterized by proliferation in the bone marrow of one or more of the myeloid (i.e., granulocytic, erythroid, megakaryocytic, and mast cell) lineages.
myocardial infarction (5 papers, 2017 to 2024). Gross necrosis of the myocardium, as a result of interruption of the blood supply to the area, as in coronary thrombosis. "As previously shown, Mdm2 inhibition also inhibits NF-κB activation, which consequently suppresses the production of proinflammatory cytokines in the heart after myocardial infarction." (PMID 29340077, 2017). "It is then appealing to hypothesize that the interaction between MDM2 and FoxO4 in the endothelium controls the inflammatory response after myocardial infarction; a hypothesis that remains unverified." (PMID 31921839, 2019). "Interestingly, MDM2 is upregulated in the cardiac tissue 24 h post-myocardial infarction and remains elevated up to 4 weeks post-infarction." (PMID 31921839, 2019).
ovarian clear cell cancer (5 papers, 2016 to 2025). An invasive malignant neoplasm that arises from the ovary and is characterized by a predominance of clear and hobnail malignant epithelial cells. "Interestingly, previous research in clear cell ovarian carcinoma (CCOC) highlighted the association of both MDM2 and PIK3CA overexpression with poor prognosis." (PMID 40149355, 2025). "High MDM2 expression is correlated with poor progression free survival in ovarian clear cell carcinoma and with poor overall survival in urothelial neoplasms of the bladder." (PMID 29451912, 2018). "We evaluated the prognostic and therapeutic value of MDM2 in ovarian clear cell carcinoma." (PMID 27659536, 2016). "For ovarian clear cell carcinoma, in which the PI3K/AKT/mTOR pathway and the MDM2 gene are prognostic factors, AKT and MDM2 inhibitors may prove to be promising therapeutic drugs in the future." (PMID 34885229, 2021).
pulmonary fibrosis (5 papers, 2020 to 2025). Chronic progressive interstitial lung disorder characterized by the replacement of the lung tissue by connective tissue, leading to progressive dyspnea, respiratory failure, or right heart failure. "Taken together, these findings suggest that ZBM may regulate the development of pulmonary fibrosis partly through the PI3K/AKT/MDM2 and PI3K/AKT/GSK3B signaling pathways." (PMID 36479180, 2022).
skin cancer (5 papers, 2017 to 2025). "Consistent with this, we want to discover a new strategy which can down-regulate the expression of MDM2 in skin-cancer cells via the alternative splicing of MDM2." (PMID 28035066, 2017). "But the report about mechanisms of hnRNPA1 regulating MDM2 expression in skin cancer cells is poorly." (PMID 28035066, 2017). "Mutations in the Hras, Pten, Pi3k, Mdm2, Tp63, Esr, Pgr, and Her2 genes, loss of Cdkn2a, Igf, and Akt, as well as MYC phosphorylation have been identified in DMBA-induced breast, blood, and skin tumor models." (PMID 41426972, 2025). "The results from ongoing clinical trials (NCT03611868, NCT03787602) may shed light on the utility of MDM2 inhibitors in skin cancer." (PMID 36768563, 2023). "Importantly, inhibition of MDM2 and LSD1 induces cell death in MCC cells and reduces the growth of MCC tumor in mice, demonstrating the therapeutic potential of using MDM2 and LSD1 inhibitors in treating this highly aggressive skin cancer." (PMID 34566942, 2021).
spindle cell tumor (5 papers, 2015 to 2025). "Fortunately, the utilization of FISH testing, which achieves a specificity of 95% and sensitivity of 100% for MDM2 gene amplification, facilitates the differentiation of DDL from other spindle cell neoplasms." (PMID 39410565, 2024). "Postoperative immunohistochemistry revealed a spindle cell tumor with myxoid stroma (S-100 negative, MDM2 weakly positive)." (PMID 41143184, 2025).
testicular germ cell tumor (5 papers, 2020 to 2024). A germ cell tumor arising from the testis.
adenosarcoma (4 papers, 2017 to 2023). A low grade malignant neoplasm characterized by the presence of a benign epithelial component (tubular and cleft-like glands) and a low grade sarcomatous component that contains varying amounts of fibrous and smooth muscle tissues. "Amplifications of MDM2/CDK4 remained significantly more prevalent in low‐grade adenosarcomas than in all PTs (Fisher's exact test, P = 0.0242)." (PMID 28267263, 2017). "PTs significantly more frequently displayed mutations affecting MED12, the TERT gene promoter and bona fide cancer genes, whereas adenosarcomas harbored a higher rate of MDM2/CDK4 and TERT gene amplifications." (PMID 28267263, 2017). "Meanwhile, MDM2, CDK4, HMGA2, and GLI1 gene amplifications are common molecular events in Müllerian adenosarcoma, often seen in patients with SO." (PMID 37810911, 2023). "A recent large next-generation sequencing study of atypical uterine polyps (polyps with atypical stromal features exhibiting some morphologic overlap with adenosarcomas) also confirmed focal gene amplifications of CDK4 and MDM2, among other loci." (PMID 35798968, 2022). "Conversely, MDM2/CDK4 amplifications, a consistent finding in approximately a quarter of adenosarcomas, were absent in PTs." (PMID 28267263, 2017). "Focal amplifications in 12q14.1‐15, encompassing the loci of MDM2 and CDK4, were significantly more prevalent in adenosarcomas than in PTs (26% vs 0, Fisher's exact test, P = 0.0155)." (PMID 28267263, 2017). "We did not identify CDK4 or MDM2 gene amplifications, pointing to significant differences between EMPs and atypical uterine polyps/adenosarcomas." (PMID 35798968, 2022). "As a limitation of our study, it is important to mention that our study cohort did not include cases of Müllerian adenosarcoma, a lesion known to harbor MDM2 amplifications in up to 28% of cases." (PMID 32352245, 2020).
benign lipomatous tumors (4 papers, 2014 to 2022). "For benign lipomatous tumors, almost all cases showed adipocyte proliferation with an absence of amplification of the MDM2 gene, except for three cases with amplified MDM2 that were reclassified as WDLS." (PMID 36164527, 2022). "In this study, we found that where there was a firm histologic diagnosis of benign lipomatous tumor or of WDL/DDL, the concordance rates of histology with MDM2 amplification results were high (92.6% and 96.5%, resp)." (PMID 25810689, 2015).
bone tumors (4 papers, 2009 to 2026). "Similar to our observation, the gain of the 12q amplicon was previously found in individual ASPS cases, and the putatively amplified oncogenes on chromosome 12q (e.g., CDK4 and MDM2) were frequently seen in patients with soft tissue and bone tumors." (PMID 35628499, 2022).